KCNH1 (potassium voltage-gated channel subfamily H member 1)
Diseases named in the same sentence as KCNH1 in open-access papers (continued):
Sharing a sentence is not in itself a finding about the gene and the disease.
ciliopathies (1 paper, 2022). "Some clinical features of KCNH1-related phenotypes, as facial and digital malformations, which are included in the phenotype spectrum of some ciliopathies, have been considered as caused by perturbations of signaling pathways, as the SHH, which is involved in morphogenesis processes." (PMID 35639255, 2022).
Hypertension (1 paper, 2021). The presence of chronic increased pressure in the systemic arterial system. "Certain genes involved in the pathogenesis of hypertension—Alb, Chrm2, Xirp1, Kcnq1, Slc5a7, Kcnh1, Ache, Crlf1 and Galr2— should also be studied." (PMID 34603037, 2021).
Hypotonia (1 paper, 2021). Hypotonia is an abnormally low muscle tone (the amount of tension or resistance to movement in a muscle). "Hypotonia was present in 26/27 (96%) individuals with dominant KCNH1 variant, in 4/6 (67%) with dominant KCNN3 variant, and in 2/3 (66%) with dominant KCNK4 variant." (PMID 33594261, 2021).
rheumatoid arthritis (1 paper, 2022). A chronic, systemic autoimmune disorder characterized by inflammation in the synovial membranes and articular surfaces. "KCNH1 expression was elevated in FLSs and synovial tissues of rheumatoid arthritis sufferers in comparation with healthy controls." (PMID 36506558, 2022).
cancer (49 papers, 2006 to 2025). A tumor composed of atypical neoplastic, often pleomorphic cells that invade other tissues. "Mutations in KCNH1, whose oncogenic properties were reported in several studies and which is largely overexpressed in different cancers, have been recently reported as causative of developmental diseases." (PMID 35639255, 2022). "KCNH1 ectopic expression has been reported in most human cancers, and its function has also been associated with intracellular signaling, cell proliferation, and tumorigenesis in a way that appears unrelated to its role in ion permeation." (PMID 35639255, 2022). "The human ether à go-go channel (hEAG1, also known as Kv10.1, encoded by the gene KCNH1) is a voltage-gated K+ channel mainly expressed in neuronal and cancer cells." (PMID 27005320, 2016). "The oncogenic voltage-gated potassium channel subfamily H member 1 (KCNH1), encodes the Ether-à-go-go 1 (EAG1, Kv10.1) potassium channel, which is overexpressed in various cancers, while inhibiting its expression or activity decreases cancer cell proliferation." (PMID 40608162, 2025). "KV10.1 (Eag1, encoded by KCNH1) is one of the best-studied ion channels in the context of cancer." (PMID 24493742, 2014). "Several cancer cell lines harbor elevated expression of KCNH1, and increasing this channel’s expression in cells can transform them into cancer-like cells." (PMID 38527087, 2024). "On the other hand, one of the most studied ion channels in cancer is the KCNH1, a voltage-gated potassium channel expressed in most human tumors." (PMID 36769377, 2023). "KCNH1 confers accelerated cancer progression through molecular mechanisms such as regulation of cell cycle, proliferation, and ciliogenesis." (PMID 35639255, 2022). "Ether-à-go-go1 (Eag1, Kv10.1, KCNH1) K+ channel is a member of the voltage-gated K+ channel family mainly distributed in the central nervous system and cancer cells." (PMID 28367272, 2017). "The Kv10.1 (KCNH1) channel, which is widely studied in cancer, is important for cell cycle progression and is regulated through the cell cycle." (PMID 24009588, 2013). "The two members of the KCNH family of voltage-gated potassium ion (K+) channels, human ether-à-go-go type 1 (Eag1 encoded by KCNH1) and human ether-à-go-go-related gene (hERG encoded by KCNH2), have been implicated in cancer development and hold promise as therapeutic targets." (PMID 40126672, 2025). "Consequently, the inhibition of KCNH1 expression and/or activity results in decreased in vitro and in vivo cancer cell proliferation." (PMID 36769377, 2023). "Interestingly, KCNH1 is reported to be upregulated in many cancers, including breast, lung, prostate, and colon; thus, its use is postulated as an early tumor marker and prognostic marker as well." (PMID 33806009, 2021). "Among others, the KCNH1 expression is decreased in calcitriol- treated cancer cells." (PMID 33806009, 2021). "These expression patterns prompted investigation of KCNH1 as a potential cancer biomarker." (PMID 24759919, 2014). "Some genes (e.g. SPINK1 in MAY and ANO4, KCTD8, COL15A1, and KCNH1 in ZMA) are related to cancer and skin properties and may have played a role in adaptation to Mayotte and Madagascar climates by increasing tolerance to thermal stress, humidity, and UV exposition." (PMID 35137043, 2022). "Based on the role of KCNH1 in cancer cell proliferation and considering that the transformation of normal keratinocytes with HPV E6 and E7 oncogenes results in increased KCNH1 gene expression, we evaluated the effect of AM upon this gene." (PMID 36769377, 2023). "Although the function of KCNH1 is better understood than that of KCNH5, both of these genes are thought to be involved in cell cycle regulation and tumour progression in cancer." (PMID 24759919, 2014). "Similarly, the use of selective shRNA and siRNA targeting KCNH1 and ORAI1 leads to an increase in cancer cell sensitivity to chemotherapeutic drugs." (PMID 33806009, 2021).
cancer (continued). "Meanwhile, it has been shown that KCNH1 and KCNH2 accelerate the proliferation of non-excitable cell-derived cancer cells, which has nothing to do with their ion conduction function." (PMID 38905316, 2024).
tumor (46 papers, 2006 to 2025). "For example, KV10.1 (KCNH1) is associated with proliferation, malignant transformation, and tumor growth, and various studies have been conducted to study inhibitors of KCNH1, such as tetrandrine (30 mg/kg/day), that reduce CCa tumor growth in vivo." (PMID 37375748, 2023). "Although further research is needed, KCNH1 overexpression is suggested to be a useful marker for monitoring tumor progression and potential metastasis." (PMID 40361464, 2025). "The analysis demonstrated that AM significantly inhibited the gene expression of the E6 and E7 HPV oncogenes and KCNH1 in the tumor mass." (PMID 36769377, 2023). "Of interest was the finding of an AM-dependent decreased gene expression of E6, E7 and KCNH1 both in vitro and in vivo, as well as the modulation of cytokine expression, Ki-67, and tumor growth inhibition." (PMID 36769377, 2023). "Kv10.1, also known as ethera-go-go-1(EAG1), is encoded by the KCNH1 gene and plays a critical role in tumor cell proliferation, angiogenesis, migration, and invasion." (PMID 36703789, 2022). "Certain types of potassium channels (known as Eag1, KCNH1, Kv10.1) are associated with the production of tumours in patients and in animals." (PMID 17022810, 2006). "Studies have shown that inhibiting KCNH1 suppresses cell proliferation and limits tumor growth." (PMID 40361464, 2025). "The second refers to an expression where the channel is not normally expressed; an example of this is the KCNH1 gene that encodes the Kv10.1 channel, whose overexpression has been reported in a wide variety of tissues that present tumor growth, which is why it is considered a tumor marker." (PMID 37511269, 2023).
neurodevelopmental disorder (5 papers, 2021 to 2026). A behavioral and cognitive disorder with onset during the developmental period that involves impaired or aberrant development of intellectual, motor, or social functions. "With increasing variants identified, the phenotypic spectrums of KCNN3 and KCNH1 are expanding, from syndromic neurodevelopmental disorder to pure epilepsy." (PMID 36683851, 2022). "Consistent with the observation in zebrafish, mutations in the human gene encoding Eag1 (KCNH1) were recently reported in individuals with two congenital neurodevelopmental disorders: Temple–Baraitser syndrome (TMBTS) and Zimmermann–Laband syndrome (ZLS)." (PMID 33647316, 2021). "It is a syndromic neurodevelopmental disorder that shared notable phenotypic overlaps with the syndrome caused by variants of potassium channel-encoding genes KCNN3 and KCNH1." (PMID 36683851, 2022).
KCNH1 also shares sentences with these, for which no sentence is quoted: glioblastoma (7 papers); hepatocellular carcinoma (4); infection (4); diabetes (3); leukemia (3); neurological disorders (3); ovarian carcinoma (3); prostate carcinoma (3); sarcoma (3); soft tissue sarcoma (3); breast tumors (2); channelopathies (2); colorectal cancer (2); epileptic seizures (2); myeloid leukemia (2); Obesity (2); prediabetes (2); retinoblastoma (2); Acute encephalopathy (1); acute leukemia (1); acute lymphoblastic leukemia (1); acute myeloid leukemia (1); Alagille syndrome (1); brain ischemia (1); catalepsy (1); cervical intraepithelial neoplasia (1); chronic lymphatic leukemia (1); chronic myeloid leukemia (1); Cognitive impairment (1); Colon cancer (1).
A further 37 diseases each share a sentence with KCNH1 in 1 paper.